PDPN (podoplanin)
Diseases named in the same sentence as PDPN in open-access papers (continued):
Sharing a sentence is not in itself a finding about the gene and the disease.
Sepsis (11 papers, 2012 to 2026). Sepsis is defined as life-threatening organ dysfunction caused by a dysregulated host response to infection. "Pharmacological inhibition of the interaction between CLEC-2 and podoplanin regulates immune cell infiltration and the inflammatory reaction during sepsis, suggesting that activation of podoplanin underlies the anti-inflammatory action of platelet CLEC-2." (PMID 29269852, 2017). "The supplementary in vivo and preliminary human data added during revision further support the translational relevance of PDPN as a therapeutic target in sepsis." (PMID 42272990, 2026). "ADAP regulates sepsis progression by controlling the TLR4-induced upregulation of PDPN to form a PDPNhi macrophage subpopulation, which exerts enhanced antibacterial functions during sepsis." (PMID 39903516, 2025). "Together, these data demonstrate that phosphorylation of ADAP at Y571, mediated by BTK, is essential for sustaining the induction of PDPN in macrophages in response to LPS or in the context of sepsis." (PMID 39903516, 2025). "ADAP is indispensable for the induction of PDPN expression in macrophages in response to LPS stimulation or bacterial infection during sepsis." (PMID 39903516, 2025). "Together, our findings reveal a mechanism whereby ADAP resets macrophage function by controlling the TLR4-induced upregulation of PDPN as a host innate immune defense during sepsis." (PMID 39903516, 2025). "Given that LPS-induced PDPN expression in macrophages to form the PDPNhi PM subpopulation in sepsis is dependent on ADAP, we next sought to elucidate the signaling pathways involved in this process." (PMID 39903516, 2025). "In sepsis, the interaction between macrophage PDPN and platelet CLEC-2 is critical for recruiting macrophages to the infection site to promote bacterial clearance." (PMID 39903516, 2025). "More recently, a new protective role for the podoplanin–CLEC-2 axis has been described, where platelets aid recruitment of podoplanin-expressing macrophages that control bacterial-induced murine sepsis." (PMID 30745334, 2019). "We further demonstrate that pharmacological blockade of the CLEC-2-podoplanin axis regulates the inflammatory reaction and immune cell infiltration during sepsis." (PMID 29269852, 2017). "Taken together these data suggest that the CLEC-2-podoplanin pathway plays a critical role in limiting inflammation during sepsis." (PMID 29269852, 2017). "In this study, we demonstrate that the podoplanin-CLEC-2 axis plays a protective role in sepsis by controlling the cytokine/chemokine storm following infection limiting organ damage." (PMID 29269852, 2017). "Using a mouse model of hematopoietic-deletion of podoplanin, PDPNfl/flVAVcre+, a significant increase in sepsis severity and tissue injury was observed compared to littermate controls following CLP." (PMID 29269852, 2017). "In this study, we show that anti-podoplanin antibody, mAb 8.1.1, modulates the inflammatory reaction following sepsis." (PMID 29269852, 2017). "Despite these findings, it remains obscure how LPS-induced PDPN expression in macrophages is precisely regulated and what the functional role of the induced PDPN+ macrophage subpopulation is during inflammatory diseases such as sepsis." (PMID 39903516, 2025). "Moreover, blockade of the PDPNhi PM subset by administration of an anti-PDPN antibody aggravates disease severity, corroborating the protective role of this unique PDPNhi PM subpopulation in host defense against sepsis." (PMID 39903516, 2025). "Induction of podoplanin (PDPN) expression is a critical response of macrophages to LPS stimulation or bacterial infection in sepsis, but how this key process of TLR4-stimulated PDPN upregulation is regulated and the effect of PDPN expression on macrophage function remain elusive." (PMID 39903516, 2025).
Sepsis (continued). "The protective effect of CLEC-2 in septicemia was partly mediated by its interaction with the podoplanin expressed on inflammatory macrophages, which limited the infiltration of immune cells into the infected site by controlling cytokine/chemokine secretion, and mitigated organ damage." (PMID 34177942, 2021). "However, in vivo, although pro-inflammatory cytokines and chemokines increased, the injection of anti-podoplanin antibody regulated the inflammatory response and immune cell infiltration during sepsis." (PMID 34177942, 2021). "Podoplanin antibody, mAb 8.1.1, regulates inflammatory response after sepsis." (PMID 34177942, 2021). "Based on the previously reported role of platelets during sepsis, and the upregulation of podoplanin on inflammatory macrophages, we hypothesize that CLEC-2 on platelets may also play a role in the early inflammatory events that gives rise to sepsis." (PMID 29269852, 2017). "Interestingly, although PDPN on inflammatory macrophages has been reported as a critical player in the inflammation control during sepsis and acute respiratory distress syndrome, the function of PDPN positive (PDPN+) macrophages in cancer has remained unexplored." (PMID 30972297, 2019). "Type I mucin-like transmembrane protein PDPN, the only known endogenous ligand for CLEC-2, is induced in macrophages in response to LPS stimulation or bacterial infection during sepsis." (PMID 39903516, 2025). "qRT-PCR for PDPN and VGEF-C clearly showed both transcripts to be increased in the CABG group and even more in the sepsis group, indicating lymphangiogenesis in both groups." (PMID 31581250, 2019). "We suggest podoplanin-CLEC-2 as a novel anti-inflammatory axis regulating immune cell recruitment and activation in sepsis." (PMID 29269852, 2017). "Here, Rayes and colleagues show that the interaction between podoplanin and its receptor CLEC-2 on platelets plays a critical role in limiting inflammation during sepsis." (PMID 29269852, 2017). "This evidence suggests that PDPN acts as a TLR4 ligand–induced cell surface protein, and its upregulation in macrophages is a key event in the macrophage response to bacterial infections during sepsis." (PMID 39903516, 2025). "When ADAP is underexpressed, LPS fails to induce PDPN expression in macrophages, resulting in a decrease in the generation of PDPNhi PMs and in aggravation of sepsis." (PMID 39903516, 2025). "The interaction of PDPN and CLEC-2 not only contributes to the formation of sepsis-related immune thrombosis but also restricts further deterioration of sepsis by controlling cytokine storm, regulating immune cell infiltration and inducing the release of complement inhibitors." (PMID 38504248, 2024). "However, the molecular mechanisms underlying the precise regulation of TLR4-dependent induction of PDPN in macrophages and the role of the PDPNhi macrophage subpopulation in sepsis immunity have not yet been elucidated." (PMID 39903516, 2025). "Surprisingly, in contrast to WT mice, there was no obvious induction of the C2 subpopulation in Adap–/– septic mice, wherein the percentage of the induced PDPNhi PM subset was only at marginal levels, suggesting that PDPN fails to be upregulated in Adap–/– PMs during sepsis." (PMID 39903516, 2025). "In addition to PDPN, ADAP is elevated in macrophages in response to LPS or bacterial challenge during sepsis, suggesting that PDPN and ADAP play related roles in modulating macrophage function during sepsis." (PMID 39903516, 2025). "Thus, ADAP provides molecular control in the pathogenesis of sepsis by regulating PDPN expression in PMs, and correction of ADAP phosphorylation and induction of the PDPNhi PM subset could provide treatment strategies for sepsis." (PMID 39903516, 2025). "Importantly, the anti-podoplanin antibody regulates the inflammatory reaction and immune cell infiltration during sepsis without inducing bleeding in the peritoneal cavity." (PMID 29269852, 2017).
thrombosis (11 papers, 2015 to 2024). "CLEC-2 expressed on the platelet surface interacts with PDPN expressed on different cell surfaces to mediate diseases such as tumor progression and metastasis, tumor-associated thrombosis, venous thrombosis, arterial thrombosis, and immune diseases." (PMID 38504248, 2024). "Podoplanin elevation after stenosis correlates with an increased risk of thrombosis, and further upregulation of podoplanin during thrombosis aggravates the condition." (PMID 34177942, 2021). "The capacity of podoplanin, up-regulated in metastatic tumours, to induce platelet activation and cancer cell arrest and extravasation, makes tempting to speculate that CLEC-2-podoplanin interactions might play a role in cancer-associated venous thrombosis." (PMID 25694214, 2015). "This study provided indirect support for the notion that non-small cell lung carcinoma patients with increased soluble PDPN levels might be more susceptible to hypercoagulability and thrombosis, as evidenced by the strong positive associations between soluble PDPN and indices of coagulation." (PMID 40741180, 2024). "Inflammatory events in the vessel wall characterize deep vein thrombosis (DVT) where reduced thrombosis was observed in CLEC-2 deficient mice or after treatment of mice with an anti-podoplanin antibody." (PMID 33114406, 2020). "To this end, we entered the following search terms into PubMed and Google Scholar: ‘cancer-associated thrombosis AND podoplanin’; ‘thrombosis AND podoplanin’; and ‘venous thromboembolism AND podoplanin’." (PMID 40741180, 2024). "Podoplanin is a type I transmembrane glycoprotein that mediates venous thrombosis, extravascular platelet activation and inflammation in atherosclerosis, and wound repair upon binding to CLEC-2." (PMID 34177942, 2021). "The presence of podoplanin in this location contributes to exacerbate deep vein thrombosis, as demonstrated by the fact that treatment with a neutralizing antibody resulted in smaller thrombi." (PMID 30736372, 2019). "In inflammation, podoplanin in the vessel wall induced thrombus formation in a murine model of deep vein thrombosis." (PMID 30745334, 2019). "In light of our observations we postulate that adhesive interactions between platelet CLEC-2 and podoplanin-expressing cells under venous shear might be physiologically important in the context of adult lymphatic maintenance, atherothrombosis, cancer-associated venous thrombosis and metastasis." (PMID 25694214, 2015). "CLEC-2 has been shown to have a critical role in deep vein thrombosis formation in mice through interaction with its ligand podoplanin, with post-mortem data suggesting a similar mechanism may occur in humans." (PMID 35805988, 2022). "Besides tumor metastasis, recent studies have demonstrated that the podoplanin-CLEC-2 interaction is important for the development of deep vein thrombosis after mechanical injury." (PMID 31553741, 2019).
cervical cancer (10 papers, 2007 to 2022). A primary or metastatic malignant neoplasm involving the cervix. "Clinical studies of human cancer tissues indicate that PDPN expression is associated with aggressive phenotypes of human cancer and is a poor prognostic marker in esophageal, oral, lung and cervical cancers." (PMID 26528756, 2015). "Analysis showed that in cervical cancer, 3/4 of structures with partial endothelial lining were positive when stained with antibodies to podoplanin." (PMID 32849870, 2020). "Our findings also confirms that Podoplanin plays an important role in cell migration and in the lymphatic spread of cervical cancer cells to regional lymph nodes." (PMID 28912668, 2017). "Podoplanin, selectively expressed in lymphatic endothelium, has been used to detect lymphatic invasion in several malignant neoplasms, including cervical carcinoma." (PMID 28912668, 2017). "In present research, after labeling with podoplanin, the lymphatic microvessels in cervical cancer were discovered mostly in interstitial tissue and periphery of the tumor but rare or even absent in the tumor tissue." (PMID 23959090, 2014). "Additionally, the expression levels of Podoplanin were also measured in 130 cervical cancer patients (FIGO stages Ib1–IIa2) using immunohistochemistry (IHC) staining." (PMID 28912668, 2017). "Hence, podoplanin was proposed as a prognostic marker for cervical cancer." (PMID 17179989, 2007).
cervical cancer (continued). "Our data also show that Podoplanin expression is negatively correlated with the OS (P = 0.004) and DFS (P = 0.006) of cervical cancer patients." (PMID 28912668, 2017). "The OS (85.2%) and DFS (80.3%) rates in the cervical cancer patients with positive Podoplanin expression are smaller than those for the patients without Podoplanin expression (OS 98.6%, DFS 95.7%)." (PMID 28912668, 2017).
invasive breast carcinoma (10 papers, 2007 to 2025). A carcinoma that infiltrates the breast parenchyma. "Paraffin-embedded sections of 177 primary invasive breast cancer, with complete clinical follow-up information for 10 years, were stained for VEGF-A, -C, -D, podoplanin and CD34 using standard immunohistochemical approaches." (PMID 17353919, 2007).
Kaposi's sarcoma (10 papers, 2007 to 2025). A malignant neoplasm characterized by a vascular proliferation which usually contains blunt endothelial cells. "In this context, it also needs to be noted that podoplanin expression is up-regulated in many tumours including Kaposi sarcoma." (PMID 20482880, 2010). "Thus, podoplanin might play a role in the development of the AIDS-associated Kaposi sarcoma, but is unlikely to modulate HIV spread in patients." (PMID 20482880, 2010).
lymphedema (10 papers, 2014 to 2024). Excess fluid collection in tissues, causing swelling. "Fibrosis in lymphedema is associated with progressive accumulation of alpha-smooth muscle actin (α-SMA) around podoplanin-expressing collecting lymphatic vessels, which are eventually obliterated in late stages of the disease." (PMID 29773802, 2018). "Deletion of podoplanin is perinatally lethal and podoplanin knockout pups have congenital lymphedema, impaired lymphatic transport, undetectable lymphatic capillaries, and absence of abdominal lacteals." (PMID 30979062, 2019). "The MMTV-PyMT; PDPN-tk mice exhibited increased incidence of cystic tumors, possibly resulting from enhanced lymphedema, when compared to control mice." (PMID 30592710, 2018). "PDPN knock-out mice exhibit impaired congenital lymphedema and lymphatic injury patterns." (PMID 31208371, 2019). "(podoplanin[+] lymphatic vessels: Sham: 4.8 ± 2.8/HPF, Lymphedema: 3.1 ± 2.5/HPF, VLNT: 6.8 ± 5.4/HPF, p < 0.0001)." (PMID 36176614, 2022). "Collecting lymphatic vessels presenting with double staining of podoplanin and α‐SMA were identified in both the lymphedema and VLNT groups." (PMID 36176614, 2022). "Upregulation of vascular endothelial growth factor C (VEGF‐C) and podoplanin was observed in the VLNT and lymphedema groups in comparison to the control group." (PMID 36176614, 2022). "The increased level of lymphedema in primary tumor tissues of MMTV-PyMT; PDPN-tk mice was confirmed by albumin immunohistochemistry." (PMID 30592710, 2018). "There was a tendency of more but not significantly increases in the expression of VEGF‐C, LYVE‐1, podoplanin, PROX‐1 and FLT4 in the lymphedema group in comparison to the normal group, suggesting that lymphangiogenesis occurs when lymphatic injury, tissue injury or lymphedema presents." (PMID 36176614, 2022). "Interestingly, the correlation of expression profiles of perilipin (PLIN)-1 and -3 and podoplanin (PDPN) has been hypothesized as a potential link between lymphangiogenesis and lipolysis, but has not yet been explored in the context of lymphedema." (PMID 38612716, 2024).